BRAF (B-Raf proto-oncogene, serine/threonine kinase)
Diseases named in the same sentence as BRAF in open-access papers (continued):
Sharing a sentence is not in itself a finding about the gene and the disease.
tumor (continued). "Moreover, we initially observed a mutual exclusion mutation pattern between RAS genes and BRAF in various tumor types, such as Pancreas and Colon26,27, which is consistent with findings from the RAS Initiative’s RAS Dialogue37." (PMID 39455841, 2024). "Tumours frequently express BRAF mutations (> 80%), specifically the V600E mutation, which has an activating missense mutation in codon 600 of exon 15 of the BRAF gene, leading to constitutive activation of the MAPK pathway, resulting in increased cellular proliferation and decreased apoptosis." (PMID 39340753, 2024). "Tumor genetics, particularly mutations in the v-raf murine sarcoma viral oncogene homolog B1 (BRAF), Neuroblastoma Ras viral oncogene homolog (NRAS), and receptor tyrosine kinase proto-oncogene (c-KIT) genes, can impact how effectively T-VEC targets and destroys cancer cells." (PMID 39429342, 2024). "In HN01, the initial presence of a BRAF mutation coincided with a PR, suggesting that the mutation may have temporarily enhanced the tumor’s response to ICIs." (PMID 39796090, 2024). "However, the authors pointed out that when BRAF-mutated tumours were considered, the ORR was 41.7% for the high-dose FOLFIRI regimen." (PMID 37932443, 2024). "For patients with tumors that are difficult to resect or require extensive surgery (stage IVb) and who have the BRAF V600E mutation, neoadjuvant dabrafenib plus trametinib can improve the chances of achieving a complete tumor resection with a reduced extent of surgery and lower surgical morbidity." (PMID 39325263, 2024). "In contrast to humans, the BRAF p.V595E mutation rarely occurs in other canine tumour types." (PMID 38787171, 2024). "BRAF mutation status is obtained from the primary tumor sampling." (PMID 39337479, 2024). "Thus, important features, which are commonly used in clinical practice were missing (e.g. PD-L1 expression on tumor cells) or available for only a subset of patients (BRAF mutational status)." (PMID 39516682, 2024). "Moreover, loss of GPX4 induced the death of BRAF-mutant therapy-resistant cells via ferroptosis in vitro and prevented tumor relapse after treatment in vivo." (PMID 38336727, 2024). "Atypical, non-V600 BRAF (aBRAF) mutations have been recognized in recent years as a unique molecular subset, partly due to the increased use of expanded molecular profiling and circulating tumor DNA (ctDNA) analysis in the management of mCRC." (PMID 38398128, 2024). "Furthermore, tumours exhibiting BRAF V600E or TERT promoter mutations are less likely to spawn iodine avid metastases and are associated with poorer patient outcomes." (PMID 37352166, 2023). "Considering the current evidence of the association between LDL and tumor progression, and the effect of LDL on MAPK activation, we aimed to study the role of LDL in PTC cells and the connection with BRAF V600E mutation as a metabolic trigger of the tumor aggressiveness." (PMID 37446330, 2023). "Notably, BCPAP cells display the overexpression of selected genes and increased glucose uptake and lactate efflux compared to Nthy-ori 3-1 cells, confirming the high glycolytic phenotype of BRAF-mutated tumours." (PMID 37198319, 2023). "Another area of interest is that of BRAF mutation-positive tumours." (PMID 37404764, 2023). "Moreover, the high-risk group had a significantly higher level of BRAF mutation frequency, tumor mutation burden, and immune cell infiltration than the low-risk group." (PMID 37361050, 2023). "BRAF mutations are associated with a lower amount of tumour stroma (p = 3.7 × 10–4)." (PMID 37596405, 2023). "This might explain the association between TSR-high tumours and tumours with a BRAF mutation, and poor prognosis." (PMID 37344790, 2023). "Besides MSI status, NGS analysis is capable of evaluating other routinely assessed, treatment-relevant biomarkers in CRC, like RAS and BRAF status as well as tumor mutational burden (TMB)." (PMID 37894457, 2023).
tumor (continued). "Interestingly, 66.7% (6/9) of BRAF V600− R patients had a tumor sample with at least 1 LOF variant vs. 37.5% (3/8) of BRAF V600− NR patients." (PMID 36901733, 2023). "Moreover, the tumour sample T10 was the only sample that presented three potential driver mutations: BRAF, ZFHX3 and telomerase reverse transcriptase (TERT) promoter." (PMID 37317665, 2023). "Interestingly, BRAF mutation status also correlates with higher tumor growth rates in PDX models (the presence indicates a higher TGR) p = 0.04, and the presence of neural invasion in histopathological sampling (the presence meaning a higher TGR) p = 0.014." (PMID 38001663, 2023). "As MSI tumours are known to originate from the serrated pathway, a BRAF-mutation might be confounding in the association between MSI and poor prognosis, as these are common in the sessile serrated pathway and are associated with poor prognosis." (PMID 37344790, 2023). "Within this study population, MSI and BRAF-mutations were often present in the same tumour." (PMID 37344790, 2023). "BRAF is an important proto-oncogene in humans, whose tumor mutation rate is approximately 8%." (PMID 36759818, 2023). "Next-generation sequencing (NGS) of the tumor showed an actionable BRAF V600E mutation and MET N375S mutation of germline origin with unknown actionability while immunohistochemistry testing revealed IDH 1/2 were wild-type." (PMID 37231247, 2023). "Some tumor cells may exhibit antibodies for the BRAF p.V600E mutation, while the Ki-67 proliferation index is generally low, though higher values have been reported." (PMID 38137148, 2023). "A possible explanation for the larger average size of BRAF-mutated tumours is a sampling bias." (PMID 37570213, 2023). "In addition to the direct correlation of AI-based BRAF mutation prediction and tumour histomorphology, the spatial visualisation of mutation prediction was also valuable for the comparative investigation of benign and neoplastic urothelium." (PMID 37570213, 2023). "BRAF mutations could indirectly modulate the tumor immune microenvironment by modulating the pyroptosis-related signaling pathways." (PMID 36911522, 2023). "We also found several microbes were dysregulated in tumor samples with the BRAF V600E mutation." (PMID 36834564, 2023). "Analyses of the mutational landscape of serrated lesions have identified an activating BRAF mutation as a key alteration in the serrated neoplasia pathway, which is present in 70%–81% of SSLs and results in the constitutive upregulation of the MAPK signaling cascade." (PMID 37219625, 2023). "Some studies showed an association between FDG uptake, tumor size, and BRAF V600E mutation." (PMID 37809246, 2023). "Tumour histology is another factor that was associated with the appearance of the BRAF mutation." (PMID 37240418, 2023). "Biopsy and sequencing confirmed BRAF V600E variants in the relapsed tumor." (PMID 36867406, 2023). "The tumor comprises subpopulations with different mutations (BRAF or KRAS) at its inception." (PMID 37958416, 2023). "Indeed, a confounding factor is the enrichment of BRAF mutations in the APC wild-type tumours (p = 1.4 × 10−10, Fisher’s exact test)." (PMID 37666855, 2023). "Univariate and multivariate analyses identified that age >45 years (P=0.014), body mass index ≥25 (P=0.008), tumor size ≥1 cm (P=0.001), capsular invasion (P=0.001), and the presence of BRAF V600E mutation (P<0.001) were significantly associated with an increased risk of CLNM." (PMID 38047112, 2023). "However, more interestingly, diclofenac is able to impair glucose uptake (in PTC and ATC, respectively) and lactate excretion (in PTC and ATC, respectively) in both the BRAF-mutated tumour cell lines." (PMID 37198319, 2023).
tumor (continued). "Interestingly, PCPs treated with BRAF/MEK inhibitors developed a prominent inflammatory infiltrate that has been associated with significant radiologic reduction in tumor volume." (PMID 36748936, 2023). "BRAF mutations, found in approximately 10% of CRCs, have been shown to associate with a worse overall survival and to only associate with survival in microsatellite stable tumours." (PMID 37596405, 2023). "In addition to the relative and overall BRAF mutation prediction, the AI assessment enabled the visualisation of the intratumour mutation heterogeneity, which allowed the investigation of the correlation of BRAF mutation with tumour histomorphology." (PMID 37570213, 2023). "However, it should be noted that important tumor driving transversion mutations also occur, e.g., the T > A mutation that causes BRAF(V600E)." (PMID 37591832, 2023). "In addition, a nomogram integrating gender, age, tumor grade, and risk score was established to predict the 1-, 3-, and 5-year survival probability of patients with BRAF V600E WT SKCM." (PMID 36704723, 2023). "We observed a higher proportion of BRAF mutated tumours in the proximal colon (p < 2.2 × 10–16)." (PMID 37596405, 2023). "The fair discrimination of tumours on the tSNE based on the type of the secondary MAPK mutation (i.e. BRAF vs. FGFR1) even suggests that this entity could be further subdivided." (PMID 38066305, 2023). "For NSCLC, recommendations comprised larotrectinib/entrectinib (unconventional SLC28A3::NTRK2 gene fusion), capmatinib (MET amplification, GCN: 16.7), afatinib (RBPMS::NRG1 gene fusion), and dabrafinib/trametinib in the case of a BRAF p.Val600Glu, and a non-V600E BRAF mutated tumor, respectively." (PMID 38136436, 2023). "Uncontrolled signals in BRAF mutant NSCLC cause tumor growth." (PMID 37046057, 2023). "However, due to the small sample size, the interpretation of the result of subgroup analysis comparing BRAF mutated and BRAF wild-type harboring tumours, makes it difficult to draw definite conclusions." (PMID 37627054, 2023). "Furthermore, we reported that the association of VEGFA/BRAF targeting with anti‐PD‐1 antibody (triple therapy) resulted in a durable response and enabled complete tumor eradication in 50% of the mice, establishing immunological memory." (PMID 37183363, 2023). "Tumours with BRAF-mutations were more often right-sided (91.2% versus 45.0%, p < 0.001), and more often poorly differentiated or undifferentiated (35.3% versus 8.4%, p < 0.001), as were MSI tumours (87.8% versus 43.5%, p < 0.001 and 39.0% versus 6.3%, p < 0.001)." (PMID 37344790, 2023). "According to other studies, tumor behavior may not only depend on the detection of the BRAF V600E mutation but also on the AF of the mutation itself." (PMID 38201541, 2023). "Autophagy is one tumor survival mechanism that could contribute to BRAF inhibitor resistance, and multiple studies support an association between vemurafenib-induced and dabrafenib-induced autophagy and tumor cell survival." (PMID 37834222, 2023). "Thus, to understand if Hif-1α regulates the expression of these metabolic genes, we used two distinct siRNAs targeting HIF1A mRNA to knock it down in BRAF-mutated tumour cells." (PMID 37198319, 2023). "Numerous neoplasms have been linked to more than 40 BRAF mutations." (PMID 38021761, 2023). "Additionally, BRAF V600E variants have a significant correlation with tumor volume, multinodular cancer, and vascular invasion." (PMID 38203635, 2023).
tumor (continued). "Thus, to experimentally validate this metabolic gene signature, we compared a BRAFV600E-mutated papillary (BCPAP) tumour cell line and the BRAF wild-type normaloid thyroid follicular epithelial cell line (Nthy-ori 3-1)." (PMID 37198319, 2023). "However, a specific mutation in BRAF, known as V600E, can lead to uncontrolled cell growth, resulting in a tumor." (PMID 37502629, 2023). "Thus, susceptibility to BRAF inhibitors alone and the success of a combinatorial approach are tumor-lineage-dependent." (PMID 37422534, 2023). "Hence, to address if the VMR-mediated transcriptional effect on glycolysis-related genes is common to other BRAF-mutated tumours, we analysed public RNA-Seq datasets from LINCS L1000 Project." (PMID 37198319, 2023). "In what we believe is one of the first clinical trials to incorporate systematic scRNAseq analysis of paired pre- and on-treatment tumor biopsies from all patients, we identified a potential mechanism underlying the cooperativity observed between BRAF/MAPK inhibition and immune response." (PMID 36702949, 2023). "Although these studies clearly report the benefit of targeted therapy in pHGG with BRAF mutation in a tumor type mostly resistant to conventional approaches, the place of this therapy in an upfront setting is still to be proven and is yet to be approved by regulatory agencies for this indication." (PMID 37124503, 2023). "Interestingly, we disclosed that VMR treatment has a marked transcriptional effect—for several metabolic genes—that is shared across multiple BRAF-mutated tumour cell lines." (PMID 37198319, 2023). "BRAF V600E mutations were detected in 75% of primary tumours and in 55% of lymph node metastases." (PMID 37352166, 2023). "Furthermore, CD44 overexpression was also associated with clinically poor prognostic features: older age, inoperable disease, stage IV at diagnosis, mutated BRAF, and high-grade tumor." (PMID 36831554, 2023). "In MSI tumours a BRAF mutation was present in 68.3% (n = 28, p < 0.001)." (PMID 37344790, 2023). "Especially, FGL2 which was upregulated in MSI CRC and BRAF-mutated CRC could lead to high tumor mutation burden." (PMID 38036953, 2023). "In addition, a BRAF-V600E mutation in the MAPK pathway can lead to the increase of drug resistance in tumor cells, which is consistent with our results, that is, that the MAPK signaling pathway is enriched in the non-responder." (PMID 36982415, 2023). "Next generation sequencing (NGS) analysis showed low tumour mutational burden (TMB) and stable microsatellite instability (MSI) status and detected a BRAF p.V600E (c.1799T>A) mutation with a variant allele frequency (VAF) of 49% in a sample with histologically estimated tumour cell ratio of 85%." (PMID 37417899, 2023). "Indeed, several trials based on the simultaneous targeting of multiple pathways are currently evaluating the effects of combined therapies in BRAF-mutated tumours, including in PTC and especially ATC." (PMID 37198319, 2023). "However, the statistical power is limited by the fact that only six tumours harboured the prognostically unfavourable BRAF V600E mutation in CMS420." (PMID 37666855, 2023). "We envision that diclofenac, having an established role in oncological practice for the treatment of cancer-related pain, may eventually be considered as an active component of new therapies targeting tumour metabolism in BRAF-mutated cancers." (PMID 37198319, 2023). "The results showed that genetic mutations in EGFR, KRAS, and BRAF could be successfully detected in the collected tumor cells even when there was only one tumor cell (sample numbers 4 and 15)." (PMID 37849806, 2023). "Notably, the highly aggressive anaplastic BRAF-mutated tumour cells (i.e., 8505c)—compared to normal thyroid cells—display higher levels of multiple metabolic genes and increased glucose uptake." (PMID 37198319, 2023).
tumor (continued). "However, RAS and BRAF mutations are early molecular tumour changes, and studies have shown a good correlation between mutational status in primaries compared to metastases, and also within different metastasis in the same patient." (PMID 34887523, 2022). "The comprehensive genomic profiling performed throughout the treatment in our study, including the ctDNA analyses, has the potential to gain valuable insights regarding tumor evolution and mechanisms of resistance to BRAF targeted therapy in BRAF V600E mutated mCRC." (PMID 36527039, 2022). "One work that analyzed the protective effect of HT in BRAF-mutated PTCs reported that patients had significantly less extracapsular extension (57.6% vs. 29.6%, p = 0.001) and smaller tumor sizes (p = 0.028), but similar rates of LNM (35.9% vs. 31.5%, p = 0.509)." (PMID 36009596, 2022). "Furthermore, HCCs with mutations in the BRAF gene have been reported to display a more aggressive clinical course with multiple tumor nodules and higher proliferation rates." (PMID 35053591, 2022). "Thus, IHC staining for BRAF V600E detection is a reliable technique compared to PCR for identifying the BRAF V600E mutation in various tumours, and it has the benefit of substantial cost and labour savings." (PMID 36428683, 2022). "Impaired HRQL may be related to rapid tumour growth driven by the BRAF mutation, and consequently, a poorer prognosis, in line with results from a meta-analysis." (PMID 36116420, 2022). "Testing in advance will offer an option for better treatment with targeted therapies against BRAF V600E mutation that could prevent the tumour from recurring." (PMID 36428683, 2022). "Among the top 20 mutation genes, mutation in the BRAF gene accounted for 78% of tumor samples, suggesting that BRAF mutation might be correlated with the development of invasive thyroid carcinoma." (PMID 35692574, 2022). "Therefore, in addition to the known mutation in CRC, BRAF mutation, transcription, and immunologic features should be evaluated to understand tumor biology and therapeutic vulnerability." (PMID 35625987, 2022). "Inconsistently, NRAS and BRAF in the context of oncogenic, which gain new and tumour-related cellular functions because of nucleotide mutations, MITF turn into oncogenic by deregulating, impacting survival systems that are also described in the general melanocyte lineage." (PMID 36551688, 2022). "The cell lines differ in their KRAS/BRAF mutational status and primary tumor or metastasis origin." (PMID 35897809, 2022). "In univariate analysis, a high DDR1 immunostaining score was significantly associated with male sex (p = 0.0195), left tumor location (p = 0.0114), BRAF wild-type status (p < 0.0001), KRAS mutated status (p = 0.0041), and absence of expression of the serrated markers Annexin A10 (p = 0.0097)." (PMID 35205677, 2022). "This may be due to the rapid tumor progression caused by BRAF gene mutation which renders these CRLM cases technically unresectable." (PMID 36077604, 2022). "Fourth, we could not assess the association between ADI and known prognostic factors, such as tumor budding, number of lymph nodes, tumor location, microsatellite instability, TILs, mutations (such as BRAF and KRAS), or histological subtypes." (PMID 35634419, 2022). "Moreover, in another study, BRAF mutational status was only screened in the KRAS wild-type tumor specimens, and for this reason, they found similar relationships with the clinicopathologic features for both mutations." (PMID 35681771, 2022). "Whether the co-occurrence between TSC1 mutations and BRAF non-V600E kinase mutations contributes to tumor development is unknown and deserves to be explored in pre-clinical studies." (PMID 35641658, 2022). "It is noteworthy that BRAF mutation could be present in other neoplasms and therefore contribute to the overall levels of ctDNA detected." (PMID 35324835, 2022).